LRP1 (LDL receptor related protein 1)
Diseases named in the same sentence as LRP1 in open-access papers (continued):
Sharing a sentence is not in itself a finding about the gene and the disease.
brain cancer (7 papers, 2011 to 2022). A primary or metastatic malignant neoplasm affecting the brain. "This study strengthens the involvement of LRP-1 in An2-mediated internalization processes taking place in brain cancer cells." (PMID 36430705, 2022). "Angiopep-2 is a peptide that has raised great interest in the treatment of brain cancer, because it binds to low-density lipoprotein receptor-related protein-1 (LRP1) of endothelial cells in the BBB, and it is also overexpressed in glioblastoma cancer cells." (PMID 31537986, 2019). "On the contrary, upregulation in brain cancers has been noted and clinical trials explore the use of LRP1 as cargo receptor to deliver cytotoxic agents." (PMID 26617523, 2015). "ANG1005 might be a particularly effective chemotherapeutic agent for the wide array of known LRP1-expressing brain and non-brain cancers, in particular those with an aggressive phenotype." (PMID 22027709, 2011). "In brain cancer, our knowledge of MT1-MMP expression within tumor grades, and its functional impact on LRP-1-mediated ligand internalization within the tumor compartment remains limited." (PMID 36430705, 2022). "Low-density lipoprotein receptor-related protein 1 (LRP1) is a cell surface receptor expressed in the BBB, brain cancers, and neurons." (PMID 34959326, 2021). "The broad distribution pattern of LRP1, and its involvement in progression, suggests that ANG1005 may have broad applicability, especially in aggressive cancers, including non-brain cancers." (PMID 22027709, 2011).
gastric cancer (7 papers, 2020 to 2025). A primary or metastatic malignant neoplasm involving the stomach. "Furthermore, CagA accumulation is significantly increased in gastric cancer tissues with LRP1 mutations." (PMID 37198664, 2023). "However, there are only two reports on LRP1 mutations in gastric cancer." (PMID 37198664, 2023). "In addition, LRP1 mutation plays a key role in the occurrence of gastric cancer." (PMID 34819038, 2021). "Further investigations of LRP1 and CAPZA1 polymorphisms and their functions are required to elucidate the pathophysiological differences between GMA and gastric cancer." (PMID 37198664, 2023). "A single-cell study of ovarian metastases from gastric cancer reported that estrogen-responsive (ER-positive) ovarian fibroblasts secrete midkine (MDK) under estrogen stimulation, which engages LRP1 on gastric cancer cells and promotes migration, invasion, and metastatic colonization." (PMID 41323395, 2025). "Besides, the knockdown of LRP1 increased the apoptosis rate of gastric cancer cells, and inhibited cell proliferation reducing the proliferation rate of HGC-27 cells from 4.4% in controls to 1.2%~1.8% in experimental groups." (PMID 38683860, 2024). "LRP1 mRNA levels in gastric cancer with LRP1 mutation were significantly lower than those without LRP1 mutation in the TCGA–Stomach Adenocarcinoma (STAD) cohort (p < 0.001)." (PMID 32098350, 2020). "Using in silico approaches to predict the role of LRP1 mutation, we found that LRP1 mRNA levels in gastric cancers harboring LRP1 mutations were significantly lower than in those without LRP1 mutations." (PMID 32098350, 2020). "We downloaded the RNA sequence data for 343 cases of gastric cancer (with/without LRP1 mutation: 26/327) from the TCGA Genomic Data Commons Data Portal and examined the differences in the LRP1 gene expression levels." (PMID 32098350, 2020). "Therefore, we downloaded RNA sequence data for gastric cancer from the The Cancer Genome Atlas (TCGA) Genomic Data Commons Data Portal and examined the differences in LRP1 gene expression levels." (PMID 32098350, 2020). "We focused on LRP1 because it had not been reported as a strongly associated gene in previous studies of advanced gastric cancer." (PMID 32098350, 2020). "By way of illustration, Low-density lipoprotein receptor-related protein 1 (LRP1) was predicted as a driver gene in Human gastric cancer cells (GC) by our method and PersonaDrive." (PMID 38683860, 2024). "In addition, VacA can induce apoptosis in gastric cancer cells such as AGS and AZ-521 via low-density lipoprotein receptor-related protein-1 (LRP1)." (PMID 39145306, 2024).
ovarian carcinoma (7 papers, 2018 to 2025). A malignant neoplasm originating from the surface ovarian epithelium. "MDK secreted from ovarian cancer epithelial cells can also regulate cancer-associated fibroblasts by binding to NCL/syndecan 2 (SDC2)/LRP1." (PMID 40429950, 2025). "On the other hand, LRP1 promotes the migration of ovarian cancer and is associated with poorer survival; as a part of a panel of nine genes, it can predict high-risk patients with poorer outcomes in ovarian cancer and other cancers." (PMID 40429950, 2025). "In addition to MDK itself, both the LRP1 and ALK receptors have been found to be associated with ovarian cancer." (PMID 40429950, 2025). "The apparent pair of MDK_LRP1 among the three groups suggested that inhibition of the MDK_LRP1 pair might be an effective therapeutic target for ovarian cancer to reduce myeloid inhibitory cell differentiation (MDSCs)." (PMID 35935940, 2022). "TM5275 has been reported to induce cell cycle arrest and apoptosis in human ovarian cancer cells in vitro, through the inhibition of interaction between PAI-1 and LRP1." (PMID 29510576, 2018).
steatosis (7 papers, 2007 to 2025). Increased lipid within the cytoplasm of cells. "In addition to upregulation of APP, the downregulation of LRP1 associated with steatosis is likely to significantly impact the ability of the liver to clear Aβ from the periphery." (PMID 36187787, 2022). "Since obese mice (ob/ob) with extensive steatosis also demonstrated decreases in hepatic LRP1 and an increase in hepatic APP, we believe steatosis or liver injury rather than alcohol are directly responsible for the modulation of these key proteins involved in maintaining Aβ homeostasis." (PMID 37298443, 2023). "The post-translational modification of LRP1 in liver may contribute to the reduction of LRP1 that occurs with steatosis, which requires further investigation." (PMID 36187787, 2022). "Interestingly and in contrast to results observed in wild-type and hepatocyte-specific LRP1 knockout mice, liver weight and steatosis were significantly lower in cholesterol-fed LRP1 NPxY mutant mice than in similarly fed control mice." (PMID 33500241, 2021). "However, ob/ob mice and NAFLD are associated with some increases in ALT and liver injury, so the distinction between liver injury and steatosis in the regulation of hepatic LRP1 and APP may be difficult to untangle." (PMID 36187787, 2022). "Thus, signaling pathways involved in triggering steatosis and signaling pathways altered by lipid accumulation during steatosis could be involved in regulation of LRP1 and APP." (PMID 36187787, 2022). "Overall, alcohol-induced changes to hepatic LRP1 and APP occurred within a wide range of liver injury and steatosis." (PMID 36187787, 2022). "The reduction in ABCA1 expression is also consistent with lower plasma HDL levels observed in the LRP1 NPxY mutant mice, whereas the lower expression levels of the lipogenic genes may account for the reduced steatosis and lower inflammation in the livers of HFHC diet-fed LRP1 NPxY mutant mice." (PMID 33500241, 2021). "Modulation of hepatic LRP1 and APP does not seem alcohol-specific, as ob/ob mice with significant steatosis also had declines in LRP1 and increases in APP expression in the liver." (PMID 36187787, 2022). "We next examined whether the downregulation of hepatic LRP1 and upregulation of hepatic APP was alcohol specific or due to liver pathology by investigating a non-alcohol model of steatosis, ob/ob mice." (PMID 36187787, 2022).
type 1 diabetes (7 papers, 2015 to 2023). "LRP1 levels are also positively correlated with triglycerides and BMI in agreement with the close association between sLRP1 and epicardial fat extension in type 1 diabetes and general population previously reported." (PMID 36805772, 2023). "Expression of the transport protein lipoprotein receptor-related protein 1 (LRP1) is downregulated in mouse brain capillaries and CSF LRP1 is increased in type 1 diabetic patients, suggesting insulin may regulate CNS LRP1." (PMID 31213970, 2019). "Interestingly, LRP1 expression is downregulated in brain capillaries of streptozotocin-injected mice and CSF soluble LRP1 is increased in type 1 diabetes patients treated with insulin for several years, suggesting that insulin might increase central LRP1, at least on the long term." (PMID 26136681, 2015).
coronary artery disease (6 papers, 2013 to 2025). "This was consistent with a previous report showing association of risk for MI and coronary heart disease with variant allele carriers of the LRP-1 polymorphism." (PMID 23874812, 2013). "Furthermore, studies in the LRP1 genetic variants are associated with an increased risk of coronary artery diseases." (PMID 25520923, 2014). "GWAS have identified LRP1 variants as major risk loci for AAA, carotid artery, and coronary artery disease." (PMID 33784254, 2021). "LRP1 variants have been identified by GWAS as major risk loci for AAA, carotid, and coronary artery disease." (PMID 33784254, 2021). "LRP1 is increasingly recognised for its central role in protection against cardiovascular disease, with mutations in the gene now implicated through genome-wide association studies as a causal factor in AAA, carotid artery and coronary artery disease." (PMID 37724952, 2023). "Because of its central role in controlling the sensitivity of VSMCs to growth factors, LRP1 has been implicated through genome-wide association and animal studies in protection against a range of arterial diseases, including AAA, carotid and coronary artery disease." (PMID 37724952, 2023).
developmental dysplasia of the hip (6 papers, 2022 to 2026). A spectrum of hip abnormalities commonly presenting in infancy involving the relationship between the femoral head and the acetabulum and that includes subluxation or dislocation at rest or upon provocation. "Low-density lipoprotein receptor-related protein 1 (LRP1) is a multifunctional endocytic receptor whose dysfunction is linked to developmental dysplasia of the hip, osteoporosis and osteoarthritis." (PMID 39865089, 2025). "Pathogenic variants in LRP1 have recently been associated with developmental dysplasia of the hip, and this variant therefore may have contributed to this phenotype in the proband." (PMID 37414152, 2023). "Preclinical studies using various mouse models have further provided evidence for the role of LRP1 in atherosclerosis, aneurysm formation, undernutrition, osteoporosis, developmental dysplasia of the hip, and Alzheimer's disease." (PMID 38950861, 2024). "Although recent studies reported bone deformities and developmental hip dysplasia in Lrp1-mutant or heterozygous knockout mice, the function of LRP1 in periosteal skeletal stem cells is essentially unknown." (PMID 39405183, 2024).
epilepsy (6 papers, 2023 to 2025). A brain disorder characterized by episodes of abnormally increased neuronal discharge resulting in transient episodes of sensory or motor neurological dysfunction, or psychic dysfunction. "This indicates that probably the LRP1 deficiency both in astrocytes and in neurons synergizes to produce the epilepsy phenotype." (PMID 37383546, 2023). "With regard to epilepsy, an enhanced expression of LRP1 was detected in foci of a kainate mouse model of drug-resistant epilepsy (DRE)." (PMID 37383546, 2023). "In the present review I discuss the attempts that have been made to understand the link of LRP1 expression in glial lineages to the generation of epilepsy, a burdening human disease." (PMID 37383546, 2023). "Genetically, MA overlaps with epilepsy-related loci (e.g., PRRT2), while MO is enriched in pain-modulatory genes (e.g., LRP1) and CGRP pathways (CALCA)." (PMID 40826382, 2025). "Improved understanding of LRP1 in NSC biology will enhance our ability to acutely harness and regulate neurogenic processes, in turn broadly impacting a number of neurobiological diseases affected by neurogenesis, including schizophrenia, mood disorders, neurodegenerative diseases, and epilepsy." (PMID 37186298, 2023). "To date, no reports are available that support an involvement of LRP1 in human epilepsy." (PMID 37383546, 2023).
hematoma (6 papers, 2018 to 2025). A hematoma is a collection of blood from a vascular structure into an extravascular space. "Haptoglobin-Hb-CD163 as well as hemopexin-heme-LRP1 (low-density lipoprotein receptor-related protein-1) is believed to be the most important endogenous scavenging pathway which participates in hematoma/blood component resolution following ICH." (PMID 30123388, 2018). "In addition, in animal model studies, the enhancement of the activity of low-density lipoprotein receptor-related protein-1 (LRP1) and the inhibition of the expression of erythrocyte integrin-related protein CD-47 can enhance endogenous hematoma clearance." (PMID 33796002, 2021). "Lrp1 has previously been shown to clear heme-hemopexin complexes after ICH, and prophylactic intraventricular administration of recombinant human LRP1 protein 20 min before ICH induction in adult mice led to a reduction in hematoma volume, BBB permeability, and other brain injury." (PMID 38283681, 2023).
Hepatic steatosis (6 papers, 2018 to 2025). Steatosis is a term used to denote lipid accumulation within hepatocytes. "Previous studies have shown that hepatic LRP1 deficiency promotes HF diet-induced hepatic steatosis and synergizes with dietary cholesterol to accelerate the progression of hepatosteatosis to steatohepatitis." (PMID 33500241, 2021). "Loss of LRP1 in the liver may lead to metabolic dysregulation and hepatic steatosis." (PMID 37425327, 2023). "This is further supported by the finding that the LDL receptor-related protein 1 (LRP1), which also controls hepatic cholesterol efflux and protects against diet-induced hepatic steatosis, recruits PIP5KL1 and PIP5K1β to the plasma membrane for PIP2 synthesis." (PMID 41032702, 2025). "Liver-specific LRP1 knockout mice have been shown to have increased liver steatosis and hyperlipidemia, indicating that LRP1 is essential for maintaining lipid homeostasis." (PMID 37425327, 2023). "Expression of LRP1 in hepatocytes is also required to limit fat-induced hepatic steatosis, lipotoxicity, insulin resistance, and steatohepatitis." (PMID 33500241, 2021). "Both wild-type and LRP1 NPxY mutant mice also showed increased adiposity with robust adipose tissue inflammation and liver steatosis, but neither group showed extensive liver inflammation when fed the HF diet without cholesterol supplementation." (PMID 33500241, 2021).
hyperlipidemia (6 papers, 2017 to 2025). "The LRP1 NPxY mutation has been shown to improve hyperlipidemia in ApoE−/− mice." (PMID 33500241, 2021). "It suggests that endothelial Lrp1 plays an active role in LDL-cholesterol clearance at basal condition and in response to hyperlipidaemia." (PMID 28393867, 2017).
ischemia (6 papers, 2013 to 2023). A hypoperfusion of the BLOOD through an organ or tissue caused by a PATHOLOGIC CONSTRICTION or obstruction of its BLOOD VESSELS, or an absence of BLOOD CIRCULATION. "We discovered that loss of LRP1 in adult NSCs causes deficits in ischemia-induced migration, which was confirmed in vitro." (PMID 37186298, 2023). "Indeed endogenous t-PA activity at LRP1 is associated with weakening of perivascular unit in ischemia and may lead to hemorrhage transformation of infarct post-ischemia." (PMID 23940734, 2013). "The differential spatio-temporal contribution of ERK1/2- and Pyk2-mediated pathways may explain the bifunctional role of LRP1 in regulating cardiac myocyte survival immediately after ischemia and cardiac remodeling in the later stages." (PMID 31080804, 2019). "The quantitative reverse transcriptase PCR assay revealed that the expression of the LRP1 and RAGE genes involved in amyloid transport was dysregulated from 2 days to 24 months post-ischemia in the CA3 area of the hippocampus." (PMID 38067191, 2023).
neuroblastoma (6 papers, 2018 to 2025). Neuroblastoma (NB) is the most common solid, extracranial childhood tumor. "Using murine BV2 (microglia) and N2a (neuroblastoma) clonal cell lines with Lrp1 deletion (KO), the Lrp1-deficient cells and their Lrp1-sufficient counterparts were infected with JCV (MOI = 0.1), and the amount of viral RNA in the supernatant at 24 hpi was measured by RT-qPCR." (PMID 41313001, 2025). "LRP1 is also expressed at high levels in high-risk neuroblastoma tissues." (PMID 35525858, 2022). "Moreover, LRP1 deficiency in neuroblastoma cell line and mice led to reduced LRP1 interaction, resulting in decreased neuronal propagation of tau." (PMID 34211387, 2021). "In addition, the neuroblastoma study revealed that overexpression of NDRG1 causes increased level of resistant-related proteins such as MDR, LRP-1, and MRP-1." (PMID 29801473, 2018). "In addition, the neuroblastoma study revealed that NDRG1 is associated with increased level of resistant-related proteins such as MDR, LRP-1, and MRP-1." (PMID 29801473, 2018). "When we examined the internalization of tau in the neuroblastoma cell line SH-SY5Y with functional LRP1 that is fluorescently labeled, we found that tau colocalized with LRP1 within punctate structures resembling endosomal/lysosomal compartments." (PMID 33930462, 2021).
osteoarthritis (6 papers, 2018 to 2025). A noninflammatory degenerative joint disease occurring chiefly in older persons, characterized by degeneration of the articular cartilage, hypertrophy of bone at the margins and changes in the synovial membrane. "Shedding of LRP-1 by MT1-MMP has been shown to play a number of roles within different cell types; for example, LRP-1 shedding in chondrocytes increases cartilage degradation in osteoarthritis by preventing endocytosis of MMP13 and ADAMTS5 aggrecanase." (PMID 39937000, 2025). "OA, osteoarthritis; LRP1, low‐density lipoprotein receptor‐related protein 1; TNF‐α, tumor necrosis factor‐alpha; IPFP‐MSCs: infrapatellar fat pad‐mesenchymal stem cells; ECM, extracellular matrix." (PMID 40171996, 2025). "Since LRP1 shedding was increased in osteoarthritis, soluble LRP1 further augmented the aggrecanase activity in cartilage by preventing its cellular uptake." (PMID 34268335, 2021).
pulmonary fibrosis (6 papers, 2015 to 2024). Chronic progressive interstitial lung disorder characterized by the replacement of the lung tissue by connective tissue, leading to progressive dyspnea, respiratory failure, or right heart failure. "It binds to collagen I and mediates collagen phagocytosis via an apolipoprotein E receptor, low-density lipoprotein receptor associated protein 1 (LRP1), promoting resolution of pulmonary fibrosis." (PMID 35111363, 2022). "The imbalance in the expression levels of LRP1 in fibroblasts of healing tissues may lead to unlimited expansion of contractile fibroblasts, thus causing or aggravating pulmonary fibrosis and participating in the pathogenesis of asthma." (PMID 33194371, 2020).
type 2 diabetes mellitus (6 papers, 2011 to 2025). A type of diabetes mellitus that is characterized by insulin resistance or desensitization and increased blood glucose levels. "However, the increase in SELENOP in the case of type 2 diabetes enhances the uptake of SELENOP via LRP1, which is related to the increase in insulin and exercise resistance." (PMID 34124127, 2021).